SNORD3B-1 (small nucleolar RNA, C/D box 3B-1)
Synonyms: U3a; U3b1; U3b2; formerly RNU3A1
Gene: Small nucleolar RNA gene on chromosome 17 (19,061,912 to 19,062,669, forward strand). Ensembl gene ENSG00000265185.
Gene Ontology:
Biological process: RNA processing
Cellular component: nucleolus
Diseases named in the same sentence as SNORD3B-1 in open-access papers:
SNORD3B-1 is named in the same sentence as 3 diseases in open-access papers, as found by Europe PMC text mining. Sharing a sentence is not in itself a finding about the gene and the disease. The quoted sentences say what the papers report.
hepatocellular carcinoma (1 paper, 2023). A malignant tumor that arises from hepatocytes. "It has also been reported that SNORD3B‐1 is highly expressed in hepatocellular carcinoma and is utilized as a diagnostic molecular marker for early‐stage hepatocellular carcinoma and AFP‐negative hepatocellular carcinoma." (PMID 37066523, 2023).
immune dysfunction (1 paper, 2022). "The dysregulation of U3 small nucleolar ribonucleoproteins genes (SNORD3B-1, SNORD3A, SNORD3B-2, SNORD3C, and SNORD3D) are related to age-related immune dysfunction, G0/G1 to S phase transition, oxidative-/ER-stress (23349890), and pathogenesis of AD." (PMID 35958988, 2022).
SNORD3B-1 also shares sentences with these, for which no sentence is quoted: schizophrenia (1 paper).